EGF (epidermal growth factor)
Diseases named in the same sentence as EGF in open-access papers (continued):
Sharing a sentence is not in itself a finding about the gene and the disease.
oral cancer (28 papers, 1994 to 2025). "The ERbB1 gene, responsible for EGF encoding, is found on chromosome 7p12 and has been associated with increased activity in oral cancer." (PMID 34765678, 2021). "For instance, epidermal growth factor (EGF) can induce epithelial–mesenchymal transition (EMT) in oral cancer cells via the Akt/Ezrin Tyr353/NF-κB pathway, thereby enhancing their motility and invasiveness." (PMID 40282437, 2025). "This method directly assesses oral cancer biomarkers using the ELISA test to determine the levels of EGF, androgen (AR), and estrogen (ER) receptors." (PMID 37370896, 2023). "Although the detailed mechanisms that drive IGF2BP3 expression in oral cancer remain to be determined, a recent study identified epidermal growth factor (EGF) as an inducer of IGF2BP3 and PDPN expression." (PMID 32957697, 2020). "EGF promotes the proliferation, invasion and epithelial mesenchymal transition of oral cancer cells." (PMID 26919242, 2016). "The present study analyzed the effects of EGF on the invasive activity of a cultured oral cancer cell line and assessed the transcription of MMP1." (PMID 24765152, 2014). "EGF was previously found to strongly stimulate migration in several oral cancer cells, including E10, and transactivation of EGFR has been found to be part of the mechanism of mitogenic effects of GPCRs in several cancer cells." (PMID 24928086, 2014). "The observations of the current study showed that EGF reduced the expression of CK19 mRNA in oral cancer cell lines." (PMID 24765152, 2014). "In conclusion, the current study identified two pathways of EGF effects on oral carcinoma cell lines." (PMID 24765152, 2014). "To enrich CSCs from oral cancer cell lines, we maintained UM1 and UM2 oral cancer cells in serum-free culture medium with bFGF and EGF." (PMID 24423398, 2013). "Thus, the downstream effect appear to be molecular-dependence, underscoring the importance of investigating MFI2-dependent EGF/FAK-signaling in oral cancer." (PMID 37309001, 2023). "Likewise, in oral cancer cells in culture, PTHrP was significantly up-regulated by EGF stimulation via ERK and p38 MAPK, contributing to the malignancy of tumor cells downstream of HER1 signaling." (PMID 35761298, 2022). "Reduction of CK19 may be an additional pathway through which EGF increases the invasive activity of oral cancer cell lines." (PMID 24765152, 2014). "The results of the present study suggested that EGF may promote the invasive activity of oral cancer cells by activating these two pathways." (PMID 24765152, 2014). "As EGF increased the invasiveness of the HSC-3 oral cancer cell line, it was assessed whether it is also likely to modulate the expression of MMP1." (PMID 24765152, 2014). "The elevated expression of epidermal growth factor (EGF), EGFR, Janus kinase (JAK) and proto-oncogene tyrosine-protein kinase Src (Src) is noted in human oral cancer." (PMID 30001383, 2018). "Therefore, EGF may be a better target for the therapy of oral cancer than EGFR." (PMID 24765152, 2014). "Targeting EGF, as an abundant EGFR ligand, may be favorable for the treatment of chemoresistant oral cancer." (PMID 24765152, 2014). "Thus, GSK-LSD1 inhibits EGF-induced signaling and proliferation without cytotoxicity in oral cancer cells." (PMID 29088714, 2017). "In addition, proliferation of cancers including oral cancer is not necessarily promoted by exogenous stimuli, such as EGF and TGF-α, and sometimes, such exogenous ligands may inhibit the growth of the cells." (PMID 32878053, 2020). "In addition, proliferation of cancer cells including oral cancer is not always enhance by exogenous EGFR ligands, such as EGF and TGF-α, and such exogenous ligands sometimes inhibit growth of the cancer cells." (PMID 33449240, 2021).
neuroblastoma (27 papers, 2013 to 2025). Neuroblastoma (NB) is the most common solid, extracranial childhood tumor. "Moreover, in neuroblastoma, expression of EGF and EGFR has been associated with aggressive behavior both in vitro and in vivo." (PMID 31293052, 2019). "We demonstrated that cathepsin D (CD) counteracts EGF-induced neuroblastoma cell growth in 2D by downregulating EGFR/MAPK signaling." (PMID 38611021, 2024). "Neuroblastoma is a tumor arising from the sympathetic nervous system, and epidermal growth factor (EGF) influences its growth and metastatic behavior." (PMID 38611021, 2024). "In both models, neuroblastoma plasticity can be orientated from a noradrenergic towards a mesenchymal identity in vitro, especially in response to EGF and TNFα factors." (PMID 37142597, 2023). "The western blotting data demonstrate that CD was in fact downregulated in neuroblastoma cells challenged with EGF." (PMID 35563171, 2022). "Neuroblastomas widely express EGFR, and we used the same EGF-mimicking peptide to target nanoconstructs into nuclei of neuroblastoma cells as well." (PMID 34777621, 2021). "Knock-down of PTPN1 in SH-SY5Y cells increased the protein phospho-tyrosine content upon EGF stimulation, as well as cell proliferation, whereas high PTPN1 protein expression in neuroblastoma tumors associated with poor prognosis." (PMID 34957126, 2021). "We previously identified neuronal leucine-rich repeat 1 (NLRR1) as a positive regulator of EGF and IGF-1 signals in high-risk neuroblastoma cells." (PMID 34277416, 2021). "In support of this notion is a study that showed depletion of ITSN1 in EGF-stimulated neuroblastoma cells resulted in a 50% reduction in the activation of AKT." (PMID 32161523, 2020). "Afatinib also induced apoptosis and blocked EGF-induced activation of PI3K/AKT/mTOR signaling in all neuroblastoma cell lines tested." (PMID 27902463, 2017). "A previous study demonstrated that expression of Cdh13 in neuroblastoma cells resulted in their inability to respond to epidermal growth factor-induced proliferation, indicating it functions as a negative regulator of neuronal cell growth." (PMID 28386779, 2017). "NBM is a stem cell permissive serum-free, bFGF-, EGF- and B27-supplemented medium to support the growth of neural crest cells, the tissue of origin of neuroblastoma." (PMID 25826368, 2015). "MAPK pathway is activated by several growth factors (e.g., PDGF, EGF) in neuroblastoma cells, where it may modulate their resistance to cytotoxic drugs, and the results confirmed the effect of RU486 in the regulation of growth-activated intracellular pathways." (PMID 33053110, 2020). "Thus, our data suggest that EGF and bFGF are important for sustained proliferation of neuroblastoma PDX cells and that these factors diminish serum-induced differentiation." (PMID 28860499, 2017). "Moreover, TGW and NH-12 neuroblastoma cell lines transfected with a T-cadherin cDNA-expressing vector lost their mitogenic potential and proliferative response to epidermal growth factor (EGF)." (PMID 40649905, 2025). "Another interesting level of cross-talk between EGF and P2X7 receptors was reported in neuroblastoma cells, in which P2X7R promoted cell proliferation that when blocked, favored differentiation to a neuronal phenotype." (PMID 37776398, 2024). "Nerve Growth Factor (NGF), Insulin-like Growth Factor (IGF), Epidermal Growth Factor (EGF), Platelet-Derived Growth Factor (PDGF) and Vascular Endothelial Growth Factor (VEGF) are major growth factor signalling pathways in Neuroblastoma." (PMID 26010602, 2015). "Our previous work showed an EGF-induced reduction in CD levels in MYCN-not-amplified SH-SY5Y neuroblastoma (NB) cells." (PMID 38611021, 2024). "Additionally, the heatmap depicting the mRNA expression (bottom part) indicates that most neuroblastoma patients display high levels of MYCN, while the mRNA levels of EGFR, EGF, MAPK1 and CTSD are low or very low." (PMID 38611021, 2024).
neuroblastoma (continued). "We analyzed the behavior of SH-SY5Y cells in response to EGF at a concentration of 20 ng/mL, which is in the range of cell growth stimulation with no toxic side effects in neuroblastomas." (PMID 35563171, 2022). "Indeed, a major direct mitogen of hepatocytes, the epidermal growth factor (EGF), stimulated MYCN gene expression in neuroblastoma cells via the recruitment of the transcription factor Sp1 to the MYCN promoter region." (PMID 33937011, 2020). "We previously hypothesized that epidermal growth factor (EGF), the main regulator of PTHLH in several cancer types, might control PTHLH in neuroblastoma as well." (PMID 31293052, 2019). "Also, in this neuroblastoma model, the downregulation of PHLDA1 caused the increased levels of ERK1/2 in epidermal growth factor (EGF)-treated cells and non-treated cells as well as increased phosphorylation of ERK1/2 in EGF-stimulated cells." (PMID 39630301, 2025).
gastric ulcer (26 papers, 2008 to 2025). An ulcerated lesion in the mucosal surface of the stomach. "The present study revealed that gastric ulceration in mice was associated with a marked increase in the mucosal EGF level." (PMID 18237397, 2008). "In rats with gastric ulcers, orogastric EGF administered in combination with sucralfate improved ulcer healing." (PMID 36759827, 2023). "A small human study showed that treatment with intravenous EGF promoted better gastric ulcer healing compared with the antiulcer treatment cetraxate hydrochloride." (PMID 36759827, 2023). "A remarkable reduction of the EGF concentration has been reported in the gastric ulcers in a large sample of patients." (PMID 31111054, 2019). "EGF expression is increased in VEGFR1/CD11b-positive cells within gastric ulcer granulation tissues during gastric ulcer healing." (PMID 25162491, 2014). "The role of growth factors VEGF, TGF-β and EGF in angiogenesis and epithelial cell migration and proliferation in gastric ulcer healing is well documented." (PMID 23484048, 2013). "EGF has been found to have therapeutic and protective effects against gastric ulcers and intestinal mucositis." (PMID 19456848, 2009). "In addition, endogenous EGF seems to play an important role in the therapeutic effect of colloidal bismuth subcitrate (De-Nol) and sucralfat in gastric ulcers." (PMID 30934722, 2019). "Moreover, EGF has been found to be involved in the gastric ulcer healing effect of Growth Hormone-Releasing Hormone (GH-RH), as well as exhibits an inhibitory effect on gastric acid secretion in isolated gastric glands." (PMID 30934722, 2019). "EGF can accelerate gastric ulcer healing by reducing bacterial colonization of the ulcer." (PMID 24001404, 2013). "It ameliorated the gastric ulcer caused by acetic acid by improving the expression of inflammatory genes such as COX-2, inhibiting negative remodeling promoted by MMP-9, increasing cell proliferation effect via EGF, and reducing cellular apoptosis by modulating caspase-3." (PMID 31979417, 2020). "This may be because the gastric ulcer healed after treatment in the DOP-200 and DOP-400 groups, leading to a decrease in EGF and VEGF levels." (PMID 38398633, 2024). "Furthermore, treatment with SGD significantly increased the levels of EGF, PGE2, SOD, and Bcl-2 and decreased the levels of TNF-α, TBARS, and caspase-3 in the gastric tissue of rats with ethanol-induced gastric ulcers." (PMID 35449820, 2022). "Animal experiments show that some compounds in Chinese herbal medicines could improve the quality of experimental gastric ulcer healing by upregulating the expression of EGF and TGF-α in the tissue around gastric ulcer." (PMID 24454509, 2013). "Studies have shown that administration of epidermal growth factor could protect against both acid-dependent gastric assaults and independent acid attacks too; there are records of numerous studies on the role of EGF in gastric ulcer healing." (PMID 32549798, 2020).
head and neck squamous cell carcinoma (26 papers, 2008 to 2025). A squamous cell carcinoma that arises from any of the following anatomic sites: lip and oral cavity, nasal cavity, paranasal sinuses, pharynx, larynx, and salivary glands. "PTX3 enhances EGF-induced migration, invasion, and metastasis in head and neck squamous cell carcinoma cells." (PMID 41373493, 2025). "Two years later, the Nie group reported non-invasive cancer detection using epidermal growth factor (EGF)-targeted gold nanoparticles (Au NPs) in human head and neck squamous cell carcinoma-bearing nude mice." (PMID 39934124, 2025). "At the same time, the production of PTX3 promotes the upregulation of epidermal growth factor (EGF) in head and neck squamous cell carcinoma cells, tumor cell migration, invasion and EGF-mediated metastasis." (PMID 33952272, 2021). "Overexpression of the epidermal growth factor (EGF) receptor (EGFR) is associated with enhanced invasion and metastasis in head and neck squamous cell carcinoma (HNSCC)." (PMID 25797258, 2015). "Indeed, we have shown that endothelial cell-derived CXCL8 and EGF have significant effects on the survival and motility of head and neck squamous cell carcinoma cells." (PMID 26287605, 2015). "Therefore, EGF may be an important regulator of HAS3 expression in ESCC, which would be especially relevant in cancers known to be responsive to EGF inhibition, such as head and neck squamous cell carcinoma and metastatic colorectal cancer." (PMID 21429221, 2011). "In head and neck squamous cell carcinoma (HNSCC) cells, EGF has been shown to function as an upstream factor of CXCL14, and the EGFR tyrosine kinase inhibitor can restore CXCL14." (PMID 34696665, 2021). "Acquired resistance to cetuximab (CTX), a monoclonal antibody that can block the binding of EGF to EGFR and inhibit the activation of downstream pathways AKT and ERK1/2, was found in head and neck squamous cell carcinomas (HNSCC)." (PMID 30927928, 2019). "Stimulation of the EGFR pathway with EGF or TGF-α induced PIM-1 upregulation and nuclear translocation in head and neck squamous cell carcinoma (HNSCC) cell lines." (PMID 27596051, 2016). "Overexpression of epidermal growth factor (EGF) and EGF receptor (EGFR) is also noted in head and neck squamous cell carcinoma (HNSCC)." (PMID 26919242, 2016). "In order to find a suppressor(s) of tumor progression in vivo for head and neck squamous cell carcinoma (HNSCC), we searched for molecules downregulated in HNSCC cells when the cells were treated with epidermal growth factor (EGF), whose receptor is frequently overactivated in HNSCC." (PMID 23762619, 2012). "Notably, epidermal growth factor (EGF) has been shown to synergize with CAF-derived cues to potentiate ECM restructuring and enhance the invasive behavior of head and neck squamous cell carcinoma (HNSCC) cells." (PMID 41583435, 2025). "In addition, in head and neck squamous cell carcinoma cells, MTSS1 was found to interact with the epidermal growth factor (EGF), strengthen the localization of the EGF receptor in the cell membrane, prolong the Erk signal and promote cell proliferation." (PMID 25295101, 2014). "EGF is involved in this ABL negative function in head and neck squamous cell carcinoma." (PMID 25803821, 2015).
viral infection (26 papers, 2013 to 2025). "We found that FGF2 and EGF stimulation allowed NR-astrocytes exposed to a single NeuroD1 virus infection to be converted into neurons." (PMID 36289433, 2022). "Growth factors are involved in the process of viral infection and EGF was shown to increase the incidence of fibrosis following SARS-infection." (PMID 34707619, 2021). "Viral infection of NPC cells led to higher levels of phosphorylated ERK1/2 after EGF treatment, which STIM1 knockdown partially reversed." (PMID 34684224, 2021). "As surface expression of EGFR is not well established in CD34+ HPCs, we first investigated EGFR surface levels in the context of WT, UL135STOP and UL138STOP virus infection using EGF-647." (PMID 27218650, 2016). "The only protein that was found to be down-regulated upon viral infection was EGF, a growth factor stimulating the growth of epidermal or epithelial tissues and some fibroblasts." (PMID 25030093, 2014). "Viral infection 18% was increased to 33.8% in the presence of EGF (an 88.7% increase)." (PMID 35746622, 2022). "Milk also contains a number of substances that may inhibit viral infection: lactoferrin, antibodies (in particular IgA), and epidermal growth factor prevent the vertical transmission of viruses." (PMID 28717367, 2017). "The only protein that was found to be down-regulated upon viral infection was EGF." (PMID 25030093, 2014). "Conversely, at lower EGF concentrations, HBV entry relies on clathrin-mediated endocytosis, resulting in increased viral infection efficiency." (PMID 38526562, 2024). "To further explore the role of miR-191-5p in modulating the effects of EGFR on viral infection and IFN-β expression, we overexpressed miR-191-5p before exposing PAMs to EGF stimulation." (PMID 39469460, 2024). "The STAT1 protein can be activated by molecules such as interferon-α, EGF, and IL6 and participate in the immune response to viral infection." (PMID 35928229, 2022). "Rac1 can be activated by a variety of stimuli, including growth factors (such as EGF and PDGF) and virus infection (HBV)." (PMID 24274578, 2013). "Interestingly, in liver sinusoidal endothelial cells, at high EGF doses, HBV is internalized through clathrin-independent endocytosis, leading to the lysosomal degradation of EGFR and suppression of viral infection." (PMID 38526562, 2024). "Additionally, hepatitis C virus (HCV) enhances expression of CXCR2 ligands in its host cell via the induction of epidermal growth factor (EGF) production, thereby recruiting neutrophile granulocytes, leading to chronic and persistent viral infection." (PMID 35730942, 2022). "Rather than inhibiting viral infection, EGF actually promotes the internalization of HBV, most likely due to the fact that EGFR may function as a co-receptor for HBV entry." (PMID 39746094, 2025). "In addition, unlike in the absence of these growth factors, we found that even a single NeuroD1-virus infection together with FGF2 and EGF could effectively induce AtN conversion by 7 dpt." (PMID 36289433, 2022).